ANKRD1 (ankyrin repeat domain 1)
Description:
May play an important role in endothelial cell activation. May act as a nuclear transcription factor that negatively regulates the expression of cardiac genes. Induction seems to be correlated with apoptotic cell death in hepatoma cells.
Synonyms: CARP; C-193; ALRP; CVARP; MCARP; bA320F15.2
Tractability: No criterion of Open Targets' tractability assessment is met for any kind of drug.
Gene: Protein-coding gene on chromosome 10 (90,912,092 to 90,921,091, reverse strand). Ensembl gene ENSG00000148677.
Subcellular location: Nucleus
Subcellular location (Human Protein Atlas): Nucleoli fibrillar center; Nucleoplasm
Pathways (Reactome):
Metabolism: PPARA activates gene expression
Gene Ontology:
Molecular function: DNA binding; histone deacetylase binding; protein binding; R-SMAD binding; RNA polymerase II-specific DNA-binding transcription factor binding; titin binding; transcription coactivator activity; transcription corepressor activity
Biological process: cardiac muscle tissue morphogenesis; cellular response to interleukin-1; cellular response to lipopolysaccharide; cellular response to mechanical stimulus; cellular response to transforming growth factor beta stimulus; cellular response to tumor necrosis factor; negative regulation of DNA biosynthetic process; positive regulation of apoptotic process; positive regulation of protein secretion; response to muscle stretch; regulation of transcription by RNA polymerase II; sarcomere organization; cellular response to hypoxia; cellular response to xenobiotic stimulus; negative regulation of transcription by RNA polymerase II; positive regulation of DNA-templated transcription; positive regulation of neuron projection development
Cellular component: cytoplasm; cytosol; nucleoplasm; nucleus; I band; myofibril; protein-containing complex; transcription regulator complex
Genetic constraint (gnomAD): Loss-of-function variants: 31 observed, 40.32 expected, observed/expected ratio (o/e) 0.77, 90% interval 0.58 to 1.04. The upper end of that interval is the gene's LOEUF score, 1.04, which puts it in group 4 of 6, group 1 being the genes least tolerant of losing a copy. Missense variants: 359 observed, 403.07 expected, observed/expected ratio (o/e) 0.89, 90% interval 0.82 to 0.97. Synonymous variants: 149 observed, 148.85 expected, observed/expected ratio (o/e) 1, 90% interval 0.88 to 1.15.
Gene-disease validity (ClinGen):
ClinGen rates the evidence that ANKRD1 causes each of these diseases.
congenital heart disease (autosomal dominant): Limited. A heart disease that is present at birth.
dilated cardiomyopathy (autosomal dominant): Limited. Cardiomyopathy which is characterized by dilation and contractile dysfunction of the left and right ventricles.
hypertrophic cardiomyopathy (autosomal dominant): Disputed. A condition in which the myocardium is hypertrophied without an obvious cause.
Homologues: Orthologues: chimpanzee ANKRD1 (99% identical), macaque ANKRD1 (96% identical), dog ANKRD1 (95% identical), rabbit ANKRD1 (93% identical), guinea pig ANKRD1 (92% identical), mouse Ankrd1 (90% identical), rat Ankrd1 (90% identical), pig ANKRD1 (79% identical), tropical clawed frog ankrd1 (67% identical), zebrafish ankrd1a (51% identical), zebrafish ankrd1b (43% identical). Paralogues in human: ANKRD2 (44% identical).
Diseases named in the same sentence as ANKRD1 in open-access papers:
ANKRD1 is named in the same sentence as 110 diseases in open-access papers, as found by Europe PMC text mining. Sharing a sentence is not in itself a finding about the gene and the disease. The quoted sentences say what the papers report.
cardiomyopathy (17 papers, 2011 to 2025). A disease of the heart muscle or myocardium proper. "Although rare variants within Ankrd1 identified in cardiomyopathy cohorts have been supported by functional effects in cellular models." (PMID 39420247, 2024). "Upregulated DEGs were associated with pro-fibrotic signaling, such as TGF-β signaling-associated genes (TGFB1, LTBP1, ANKRD1) and other cardiomyopathy-related signaling, such as the MAPK cascade (ADRA1A, EGR1, IL6R)." (PMID 37084237, 2023). "Together with their strong induction during cardiac disease and the identification of causative Ankrd1 gene mutations in cardiomyopathy patients, this suggests their important roles in cardiac development, function, and disease." (PMID 24736439, 2014). "Ankrd1 is associated with the pathogenesis of cardiomyopathy." (PMID 40362467, 2025). "Pathogenic variants in ANKRD1 have been implicated in cardiomyopathies and septal defects." (PMID 41510282, 2025). "While the transcriptional identities revealed a unique response to postnatal growth, immature myocardial tissue was generally enriched in factors related to cell division and fetal CM factors such as Nppa and Ankrd1, which are also associated with cardiomyopathy." (PMID 35050211, 2021). "One of the promising lines of future studies on Ankrd2 could be to identify mutations in Ankrd2 gene that are linked to these cardiomyopathies as has been done for Ankrd1/CARP." (PMID 22016770, 2011). "Consequently, studying the effect of variants in Ankrd1 on clinical phenotype in large family pedigrees or patient cohorts may help to clarify the relationship between Ankrd1 variation and cardiomyopathy." (PMID 39420247, 2024). "Ankyrin repeat domain 1 (Ankrd1), a transcriptional target of Yes-associated protein (YAP), is linked to cardiomyopathy." (PMID 40362467, 2025). "Further emphasizing the role of Ankrd1 in cardiac diseases, its expression is also upregulated in desmin-related cardiomyopathy, where Ankrd1 interacts with the type III intermediate filament desmin." (PMID 39420247, 2024). "These diverse findings across various forms of cardiomyopathy highlight the complex role of Ankrd1 in cardiac pathophysiology." (PMID 39420247, 2024). "Being highly induced during periods of stress and various forms of cardiomyopathies, ANKRD1 has the potential to serve as a cardiac biomarker with possible diagnostic and prognostic utility." (PMID 28672880, 2017). "Historically, research on Ankrd1 predominantly addressed its implications in cardiomyopathies." (PMID 39420247, 2024). "Research has demonstrated Ankrd1’s association with several cardiovascular conditions, including hypertrophic cardiomyopathy (HCM), dilated cardiomyopathy (DCM), ischemic cardiomyopathy (ICM), and drug-induced cardiomyopathy." (PMID 39420247, 2024). "We also found several VUSs in all four patients, including variants in genes whose loss of function is a known mechanism of cardiomyopathies, such as ANKRD1 and TNNI3, but whose role in skeletal muscle has not yet been fully described." (PMID 39063061, 2024). "However, several genes that have been implicated in cardiomyopathy did demonstrate large differences between normal controls and HCM patients, including ANKRD1, FHL2, and TGFB3." (PMID 32344918, 2020). "The study shed light on the functional role played by CARP in cardiomyopathies and suggested that Ankrd1 gene therapy or modulation of CARP activity could be viable therapeutic strategies against different types of cardiomyopathies." (PMID 23227174, 2012). "However, large scale human genetic studies of cardiomyopathy found that Ankrd1 did not have a significant overall excess of variants in cases." (PMID 39420247, 2024). "Importantly, cardiac ANKRD1 has been shown to be highly induced in various cardiomyopathies and in heart failure, although it is still unclear what impact this may have on the pathophysiology of heart failure." (PMID 28672880, 2017).
cardiomyopathy (continued). "A few lncRNAs are located in the introns of cardiomyopathy-related genes (e.g., TTN, ACTC1, TPM1, JPH2, ANKRD1, DTNA, TMPO, and FHL2) or physically close to these genes." (PMID 32344918, 2020).
heart failure (17 papers, 2012 to 2025). Inability of the heart to pump blood at an adequate rate to meet tissue metabolic requirements. "Thus, in Cyc cells we observed higher expression of genes encoding Nppa, Ccl5, Ctgf and Ankrd1, which have been shown to be associated with heart failure in earlier studies." (PMID 25799225, 2015). "The mutations of various genes encoding the proteins around the Z-disc, such as ANKRD1, DES, FLNC and CSRP3, are known to cause abnormal responses to mechanical stress, resulting in heart failure." (PMID 39195917, 2022). "Other studies have demonstrated that the elevation of ANKRD1 expression in DCM heart samples correlates with the progression of heart failure, and this reflects the increased expression that we saw in the HCM patients." (PMID 32344918, 2020). "In the future, it would be interesting to decipher the interaction between these eight heart failure-related microRNAs and ANKRD1 in cardiac lineages and in vivo platforms." (PMID 28672880, 2017). "ANKRD1 has been proposed to be a potential biomarker for cardiac remodeling and disease progression in dilated cardiomyopathy, cardiac hypertrophy and heart failure." (PMID 28672880, 2017). "Both proANP and BNP are natriuretic peptides well accepted for their diagnostic value as markers for heart failure, thus pointing to the potential of ANKRD1 as a useful reflector of the onset and progression of heart failure." (PMID 28672880, 2017). "Upon activation by hypertrophic stimuli and during heart failure, ANKRD1 expression in cardiomyocytes is highly and rapidly up-regulated, suggesting its importance in pathological cardiac remodeling." (PMID 28672880, 2017). "Ankyrin repeat domain 1 (Ankrd1), a transcriptional regulator of Gata4 signaling which is consistently increased in human heart failure, was found to be diminished by 2.5-fold (p < 0.001) in knockout heart tissue." (PMID 28673258, 2017). "The other heart failure-related microRNA, miR-34a-5p, which was found upregulated in the serum of heart failure patients, is predicted to target ANKRD1 by both TargetScan and miRanda." (PMID 28672880, 2017). "Consistent with this suggestion, induced overexpression of ANKRD1 in rats contributes to the pathogenesis of heart failure." (PMID 28672880, 2017). "Since its discovery in 1995, the Ankrd1 gene transcript has attracted significant interest owing to its persistent upregulation in patients with cardiac hypertrophy and heart failure." (PMID 23227174, 2012). "Hypertrophic stimulation and heart failure rapidly induce Ankrd1 expression in cardiomyocytes." (PMID 36361958, 2022). "In addition, ankyrin repeat domain 1 (ANKRD1) expression has been shown to be upregulated in LVs of heart failure patients and it was also upregulated in VEGFR-1 TK−/− LVs." (PMID 33802976, 2021). "Since apoptosis is considered to play an essential role in heart failure progression, one school of thought is that the pro-apoptotic actions of ANKRD1 may be an adverse contributing factor." (PMID 28672880, 2017). "Interestingly, three of the microRNAs, miR-1, miR-29 and miR-133, were reported to be dysregulated in cardiac hypertrophy model and heart failure, suggesting possible regulatory effects of microRNA on the expression of ANKRD1 in the diseased hearts." (PMID 28672880, 2017). "It has been reported that increased expression of the Ankrd1 gene in the left ventricular myocardium is induced by various hypertrophic stimuli, both in animal models and in heart failure patients with dilated cardiomyopathy (DCM) or ischemic cardiomyopathy (ICM)." (PMID 23227174, 2012). "Recent studies have also indicated that the Ankrd1 gene is strongly upregulated in the hearts of both hypertrophic animal models and those of heart-failure patients with dilated cardiomyopathy (DCM), ischemic cardiomyopathy (ICM), or arrhythmogenic right ventricular cardiomyopathy (ARVC)." (PMID 23227174, 2012).
heart failure (continued). "Niches 2 and 3 were enriched in ACM relative to donor controls and contained cardiac myocytes expressing heart failure markers (NPPA, NPPB, and ANKRD1)." (PMID 39763850, 2024). "On molecular level, myocardial ANKRD1 and serum adiponectin correlated with low BAX/BCL-2 ratios, indicative of antiapoptotic tissue propensity observed during the worsening of heart failure." (PMID 25961010, 2015). "Notably, CM1 is enriched with genes classically increased in adult heart failure such as ANKRD1 and NPPB, which highlights an important difference in myocyte cell state diversification between heart failure and single ventricle hearts." (PMID 40502733, 2025). "We demonstrated that ANKRD1 does not significantly modulate heart failure; nevertheless, the genetic ablation of Ankrd1 blunted the cardiac damage/remodeling and preserved heart function during post-MC DCM." (PMID 36551326, 2022). "In addition, in our analysis results, NPPA, NPPB, COL1A2, ASPN, ANKRD1 and CTGF were all confirmed to be closely related to heart failure in dilated cardiomyopathy in various studies." (PMID 34970603, 2021). "It has been reported in the literature that Ankrd1 can be regulated by Ang II through its type 1 receptor AT1R and directly participate in the process of cardiomyocyte apoptosis and hypertrophy and has become a new potential target for treatment of heart failure." (PMID 36361958, 2022).
dilated cardiomyopathy (15 papers, 2012 to 2025). "Ankrd1 binds to talin-1 in cardiac muscle cells, and Ankrd1 mutations in dilated cardiomyopathy result in a loss of this binding." (PMID 40362467, 2025). "In the CardiacMeso-fated segment, Myl7 and Id2 were reduced relative to controls, as was Ankrd1, a gene implicated in sarcomere-binding and dilated cardiomyopathy that is known to be upregulated with overexpression of Mesp1." (PMID 36994838, 2023). "The up-regulation of ANKRD1 has been linked to various cardiac diseases including cardiac hypertrophy, dilated cardiomyopathy, ischemic cardiomyopathy and arrhythmogenic right ventricular cardiomyopathy." (PMID 28672880, 2017). "In another study, three missense heterozygous mutations in ANKRD1 (Pro105Ser, Val107Leu and Met184Ile) were identified in four patients with dilated cardiomyopathy." (PMID 28672880, 2017). "A role for Ankrd1 in muscle pathology is suggested by findings that dilated cardiomyopathies may be linked to Ankrd1 mutations." (PMID 23914941, 2013). "Numerous studies suggested that ANKRD1 is mainly involved in disease progression and adaptive responses of cardiac hypertrophy, dilated cardiomyopathy and cardiac fibrosis." (PMID 39285846, 2024). "Ankyrin repeat domain 1 (ANKRD1), encoding for the cardiac ankyrin repeat protein (CARP), has been found to be upregulated in hypertrophic stimuli, dilated cardiomyopathy, hypertrophic cardiomyopathy, and heart failure." (PMID 38994368, 2024). "(C) Quantitative real-time PCR (qRT-PCR) analysis for MYPN, PALLD, and ANKRD1 on LV biopsies from dilated cardiomyopathy (DCM) (n = 15) and ischemic cardiomyopathy (ICM) (n = 15) male patients vs." (PMID 36927816, 2023). "The differentially expressed genes included several causative genes of congenital heart defects, hypertrophic cardiomyopathy, congenital long-QT syndrome, muscular dystrophy, and dilated cardiomyopathy (e.g., Acta2, Ankrd1, Scn4b, Ano5, Rpl3l, Cenpf)." (PMID 35942699, 2022). "Indeed, reducing Ankrd1 protein levels has been demonstrated to prevent development of dilated cardiomyopathy in mice." (PMID 34745373, 2021). "While MLP knockouts develop dilated cardiomyopathy, MLP/Ankrd1 double knockout mice display normal cardiac morphology and systolic function." (PMID 34745373, 2021).
ovarian carcinoma (15 papers, 2009 to 2025). A malignant neoplasm originating from the surface ovarian epithelium. "Moreover, ANKRD1 has been confirmed to be associated with chemotherapy resistance in various tumors, including ovarian cancer and lung cancer." (PMID 38402174, 2024). "These include genes such as PAEP, which encodes the protein glycodelin, a lipocalin protein associated with reproductive cancers including breast cancer, ISG15, a prognostic marker in breast cancer, and ANKRD1, which has been associated with lung and ovarian cancer." (PMID 34681087, 2021). "A previous study reported that a gene homologous to ANKRD1 (ankyrin repeat domain 1[cardiac muscle]) is associated with the platinum sensitivity in ovarian cancer cell lines, and decreasing ANKRD1 expression is a potential strategy to sensitize tumors to platinum-based drugs." (PMID 32487244, 2020). "Among these, ANKRD1, a member of the ankyrin repeat protein family, has been documented to be pivotal in enhancing radiotherapy sensitivity in ovarian cancer, as evidenced by previous studies." (PMID 39748197, 2025). "Ovarian cancer: in ovarian cancer, the overexpression of Ankrd1 significantly impacts the disease’s pathophysiology and treatment outcomes by modulating endoplasmic reticulum (ER) stress-related apoptosis pathways." (PMID 39420247, 2024). "For example, ANKRD1 is highly expressed in ovarian cancer and will increase the sensitivity of ovarian cancer cells to cisplatin after knockdown to enhance the therapeutic effect." (PMID 37702613, 2023). "In addition, recent study has revealed that ANKRD1 expression decreased the sensitivity of ovarian cancer to drugs." (PMID 37277814, 2023). "Additionally, down-regulation of ANKRD1 expression increased the sensitivity of ovarian cancer to cisplatin." (PMID 37277814, 2023). "For instance, overexpression of ankyrin repeat domain 1 (ANKRD1) or pleckstrin homology like domain family A member 1 (PHLDA1) in ovarian carcinoma correlates with poor survival, and upregulation of these proteins in OC cell lines modulates cell apoptosis via the ERS pathway." (PMID 37817482, 2023). "Furthermore, ANKRD1 plays a significant role in regulation of apoptosis in human ovarian cancer cells." (PMID 30291293, 2018). "Interestingly, Ddr2, Ereg, Glipr1, Calcr, and Ankrd1, all up-regulated in STOSE cells, have been shown to be up-regulated in primary tumors and ovarian cancer cells." (PMID 24672774, 2014).